MRE11 (MRE11 double strand break repair nuclease)
Diseases named in the same sentence as MRE11 in open-access papers (continued):
Sharing a sentence is not in itself a finding about the gene and the disease.
microcephaly (4 papers, 2016 to 2024). A congenital or acquired developmental disorder in which the circumference of the head is smaller than normal for the person's age and sex. "Similarly, mutations in MRE11 have also been shown to underlie craniofacial anomalies such as a small lower jaw, together with microcephaly as part of the rare Ataxia Telangiectasia-like disorder." (PMID 34095113, 2021). "Recent patients with mutations in MRE11 have also been reported to have microcephaly." (PMID 26908596, 2016). "Furthermore, role of MRE11 was also revealed in microcephaly, cognitive disabilities and cerebellar degeneration, but so far only one article reported subtantially reduced level of MRE11 and other members of MRN complex in AD patients." (PMID 38722788, 2024). "Developmentally, these phenotypes are thought to arise in part through extensive neuroepithelial apoptosis, and consistent with these observations in humans, neural stem cell-specific conditional deletion of Nbs1 and Mre11 in mouse embryos results in microcephaly." (PMID 34095113, 2021). "Furthermore, neural tissue-specific disruption of Nbs1 and Mre11 via Nestin-cre conditional gene targeting, results in microcephaly as a consequence of massive neuroepithelial cell apoptosis." (PMID 26792133, 2016).
NBS-like disorder (4 papers, 2015 to 2021). "Multiple missense variants of MRE11 have been linked to human diseases including progressive myoclonic ataxia (PMA, MRE11A47V), Nijmegen breakage syndrome-like disorder (NBSLD, MRE11D113G), and A-TLD." (PMID 34440334, 2021).
rheumatoid arthritis (4 papers, 2019 to 2025). A chronic, systemic autoimmune disorder characterized by inflammation in the synovial membranes and articular surfaces. "Rheumatoid arthritis patients have lower levels of MRE11, which shortens T-cell lifespan; this condition can be reversed by overexpressing MRE11." (PMID 39759116, 2025).
uterine endometrioid carcinoma (4 papers, 2019 to 2022). "Consistently, the mutation of MRE11 (G285C) identified in uterine endometrioid carcinoma exhibited a similar cellular phenotype as the UFMylation-defective mutant MRE11 (K282R)." (PMID 35884562, 2022). "Here, we showed that a pathogenic MRE11(G285C) mutation detected in uterine endometrioid carcinoma (TCGA database) exhibited a similar cellular phenotype with the UFMylation-defective mutant MRE11(K282R), suggesting that the role of the MRE11 UFMylation is closely associated with tumorigenesis." (PMID 30783677, 2019). "Interestingly, a pathogenic variant of MRE11 (MRE11G285C) in uterine endometrioid carcinoma displays a similar cellular phenotype with the UFMylation-defective variant of MRE11 (MRE11K282R), implying that MRE11 UFMylation is very likely to be associated with tumorigenesis." (PMID 34440334, 2021).
esophageal squamous cell carcinoma (3 papers, 2020 to 2021). Esophageal squamous cell carcinoma (ESCC) is a type of esophageal carcinoma (EC) that can affect any part of the esophagus, but is usually located in the upper or middle third. "Moreover, UBQLN4 binds to MRE11 and promotes MRE11 degradation, leading to cisplatin-resistance in cancer cells, i.e., esophageal squamous cell carcinoma (ESCC)." (PMID 34440334, 2021).
lymph node metastasis (3 papers, 2015 to 2021). "However in multivariable analysis, only larger tumor size, lymph node metastasis, and high MRE11 expression in cancer tissues were significant risk factors." (PMID 33927349, 2021). "The findings of this study also demonstrate that MRE11 overexpression is significantly related to lymph node metastasis, distant metastasis and TNM stage." (PMID 31221177, 2019).
lymphoma (3 papers, 2007 to 2021). A malignant (clonal) proliferation of B- lymphocytes or T- lymphocytes which involves the lymph nodes, bone marrow and/or extranodal sites. "Furthermore conditional deletion of MRE11 in B-lymphocytes prevented the development of IgH–MYC translocated lymphomas and triggered conspicuous DDR responses, suggesting that MRE11 counteracts MYC-induced RS." (PMID 34201047, 2021).
pancreatic cancer (3 papers, 2006 to 2020). "We conclude that Claspin and associated regulatory factors including Mre11 and Chk1 could be therapeutically targeted by E1B19K-deleted oncolytic viruses and/or novel inhibitors to better manage treatment-insensitive pancreatic cancers in particular." (PMID 26872382, 2016).
serous ovarian cancer (3 papers, 2014 to 2023). "Approximately 50% of high-grade serous ovarian cancers are characterized by HR deficiency, which involves mutations in BRCA1/2, the MRN complex (MRE11, RAD50, NBS1), ATM, RAD51C/D, PALB2, BRIP1, BARD1, and other genes." (PMID 31572446, 2019).
Adenovirus infection (2 papers, 2017 to 2025). "Adenovirus infection induces γH2AX and targets different proteins involved in DNA repair (MRE11, ligase IV and DNA-PK), leading to their inactivation/relocalization/degradation." (PMID 29228615, 2017). "Furthermore, unlike adenovirus infection, which inactivates MRE11, HSV-mediated AAV replication is enhanced by host MRE11." (PMID 40284937, 2025).
ciliopathies (2 papers, 2016). "It is intriguing that the same study identifying CEP164 mutations as causative for a subset of nephronophthisis-related ciliopathies also identified causative mutations in MRE11." (PMID 27335639, 2016). "It is presently unclear how or why specific mutations in MRE11 in particular can give rise to ciliopathies." (PMID 27335639, 2016). "Indeed, given the young age and small cohort of current ciliopathy patients with causative mutations in either FAN1 or MRE11, it is too early to determine if these patients have an increased risk of developing cancer." (PMID 27335639, 2016). "Further, a recent study also showed that mutations in MRE11, ZNF423 and CEP164, genes which encode proteins that function within the DDR, can cause nephronophthisis, providing another link between DDR signalling and ciliopathies." (PMID 26908596, 2016).
Cockayne syndrome (2 papers, 2016 to 2022). A multisystem condition characterized by short stature, a characteristic facial appearance, premature aging, photosensitivity, progressive neurological dysfunction, and intellectual deficit. "Functionally relevant interactions with TRF2 at low incidence have been reported for other TRF2 interaction partners, including Mre11/Rad50/Nbs1, XPF/ERCC1 and Cockayne syndrome group B protein." (PMID 26799419, 2016).
head and neck cancer (2 papers, 2013 to 2019). A primary or metastatic malignant neoplasm affecting the head and neck. "In the current preliminary study we screened the selected regions, where most of already known molecular variants of the RAD50 and MRE11 gene occur, among 358 head and neck cancer patients and 506 controls." (PMID 24079363, 2013).
HIV-1 infection (2 papers, 2009 to 2021). The type species of lentivirus and the etiologic agent of acquired immunodeficiency syndrome (AIDS). "Although the GFP reporter assay indicated involvement of ATM and DNA-PKcs in HIV-1 infection consistent with previous reports, the sequence analyses of the host-virus junctions revealed that Mre11 and NBS1 were also involved in HIV-1 infection." (PMID 20003485, 2009).
Huntington disease (2 papers, 2023). Huntington disease (HD) is a rare neurodegenerative disorder of the central nervous system characterized by unwanted choreatic movements, behavioral and psychiatric disturbances and dementia. "Conversely, the number of MRE11 foci progressively increases to reach its maximum 24 h post-irradiation in cells from aging syndromes (e.g., Hutchinson–Gilford progeroid syndrome, Huntington disease, and Usher syndrome)." (PMID 37626928, 2023).
malaria (2 papers, 2015 to 2020). Malaria is a serious and sometimes fatal disease caused by a parasite that commonly infects a certain type of mosquito which feeds on humans. "Overall, our study provides a comprehensive functional analysis of MRE11′s role in Plasmodium development during the mosquito stages and offers a potential target for therapeutic intervention during malaria parasite transmission." (PMID 33287434, 2020). "Overall, we have shown that MRE11 is a key regulator of malaria parasite transmission and its deletion results in deregulated transcription of essential genes across various key biological processes." (PMID 33287434, 2020). "Since Mre11 is involved in the upstream DDR pathway, which is common to all eukaryotic DSB repair mechanisms, it is likely that inactivation of PfalMre11 function could render the malaria parasites vulnerable to DNA damage." (PMID 25938776, 2015).
medulloblastoma (2 papers, 2011 to 2022). A malignant, invasive embryonal neoplasm arising from the cerebellum. "Inherited or somatic mutations in the MRE11, RAD50 and NBN genes increase the incidence of tumours, including medulloblastoma (MB)." (PMID 35839783, 2022).
promyelocytic leukemia (2 papers, 2020 to 2021). "Concerning the restriction phenotype of Mre11, formation of protein complexes known to restrict HSV-1 replication, termed PML (promyelocytic leukemia) nuclear bodies (PML-NBs) or nuclear domain 10 bodies, is sensitive to Mre11 depletion." (PMID 33563816, 2021).
prostate tumor (2 papers, 2019 to 2022). "Our data propose that the loss of MRE11 activity should be synthetically lethal with CDK9 inhibitors, and in this context, it becomes important to asses if such losses exist in prostate tumors." (PMID 35164752, 2022). "The scatter plot of IHC score revealed that elevated MRE11 was significantly expressed in prostate tumor tissues (P=0.011)." (PMID 31413753, 2019).
spinocerebellar ataxia with axonal neuropathy (2 papers, 2020 to 2022). "For example, mutations in MRE11, TDP1 and aprataxin (APTX) result in neurodegenerative disorders such as A-T like disease (ATLD), spinocerebellar ataxia with axonal neuropathy (SCAN1), and ataxia-oculomotor apraxia-1 respectively." (PMID 32284789, 2020).
acute leukemia (1 paper, 2013). A clonal (malignant) hematopoietic disorder with an acute onset, affecting the bone marrow and the peripheral blood. "With this in mind, we decided to simultaneously analyze the alterations in MRE11, RAD50 and NBN genes in Polish children with acute leukemia." (PMID 24093751, 2013).
acute myeloid leukemia (1 paper, 2016). Acute myeloid leukemia (AML) is a group of neoplasms arising from precursor cells committed to the myeloid cell-line differentiation. "Furthermore, Cal51 breast cancer cells and various acute myeloid leukemia (AML) cell lines with deficient Mre11 showed hypersensitivity to KU58948 and BMN673, respectively." (PMID 27642590, 2016).
Alzheimer disease (1 paper, 2022). A progressive, neurodegenerative disease characterized by loss of function and death of nerve cells in several areas of the brain leading to loss of cognitive function such as memory and language. "Aberrancy in MRE11 nuclease activity is associated with various human diseases, such as Alzheimer’s disease (AD) and cancers." (PMID 36077176, 2022).
anal carcinoma (1 paper, 2017). "MRE11 has no predictive value in the analysis of relapse-free survival after chemo-radiotherapy in anal cancer and does not add to the prognostic value of p16 and tumour-infiltrating lymphocyte scores." (PMID 28641314, 2017).
Atrophy (1 paper, 2017). Any weakening or degeneration, especially through lack of use. "In this respect, the conditional inactivation of Mre11 determines early cerebellar atrophy and embryonic lethality in murine models." (PMID 29170652, 2017).
cardiomyopathy (1 paper, 2012). A disease of the heart muscle or myocardium proper. "In the myocardium, Dox-induced cardiomyopathy was associated with an increase in γH2AX expression and a reduction in Rad51 and MRE11 expression and increased apoptosis." (PMID 22384017, 2012).
childhood leukemia (1 paper, 2013). An acute or chronic leukemia that occurs during childhood. "In the current study we screened the selected regions, of the MRE11, RAD50 and NBN gene, where most of already known molecular variants occur, among 220 childhood leukemia samples and controls." (PMID 24093751, 2013).
chordoma (1 paper, 2025). Chordomas are rare malignant tumors arising from embryonic remnants of the notochord in axial skeleton. "Specific mutations, such as MRE11 (p < 0.01) and ARID5B (p < 0.05), were significantly enriched in pediatric chordoma compared to adults, highlighting potential age-specific genetic differences in chordoma." (PMID 39941902, 2025).
chromosome instability syndromes (1 paper, 2023). "Traditionally, the MRE11/RAD50/NBN deficiency causes chromosome instability syndromes in humans." (PMID 37024481, 2023).
colorectal tumors (1 paper, 2021). "Clinically, mutations in MRE11 occur in the majority of MMR deficient colorectal tumors, and are associated with increased susceptibility to CRC." (PMID 34201502, 2021). "Thus, targeting MRE11 to sensitize colorectal tumor cells considering MSI status may be an interesting approach to overcome resistance and expand antineoplastic combinations." (PMID 34201502, 2021).
cyst (1 paper, 2021). A sac-like closed membranous structure that may be empty or contain fluid or amorphous material. "Several of the meiotic-related genes change their expression in the cyst stage, including Hop1, Mre11, and Smc6, suggesting that the process continues until the end of the differentiation process." (PMID 34946882, 2021).
diffuse large B-cell lymphoma (1 paper, 2021). "In diffuse large B-cell lymphoma (DLBCL) cells, the expression of key MMEJ proteins, including Lig I, Lig III, PARP1, CtIP, and MRE11 elevates, while the level of C-NHEJ factors decreases." (PMID 34732266, 2021).
emphysema (1 paper, 2024). "Next, we determined Pict1 and Mre11 mRNA and protein levels using lung tissue obtained from mice exposed to cigarette smoke for 3 weeks and 8 months, where the latter induced emphysema." (PMID 39578839, 2024). "Together, our data suggest decreased PICT1 and MRE11 expression in ATII cells in the murine model of cigarette smoke-induced emphysema." (PMID 39578839, 2024). "We found that PICT1 and MRE11 interaction was decreased in smokers and emphysema patients, in mice exposed to cigarette smoke for 3 weeks, and in the murine model of this disease." (PMID 39578839, 2024). "Moreover, MRE11 levels were decreased after mice exposure to cigarette smoke for 3 weeks and in emphysema." (PMID 39578839, 2024). "We identified PICT1 and MRE11 interaction and decreased MRE11 levels in ATII cells in emphysema." (PMID 39578839, 2024). "Our results indicate the lowest MRE11 mRNA and protein levels in ATII cells in individuals with emphysema." (PMID 39578839, 2024). "We did not see significant differences in PICT1 and MRE11 levels in lung tissue after 3 weeks of exposure to cigarette smoke and in emphysema." (PMID 39578839, 2024). "Also, reduced MRE11 and PICT1 levels in human and murine emphysema suggest DSB repair defects, which can lead to impaired formation of the MRN complex." (PMID 39578839, 2024).
Epstein-Barr virus infection (1 paper, 2022). An infection that is caused by Epstein-Barr virus. "Finally, four significant KEGG enrichment pathways were identified (P < 0.05): beta-Alanine metabolism (SMOX, HIBCH), Pathways in cancer (GLI2, AR, TXNRD3, TRAF3, FGF16), Non-homologous end-joining (MRE11), Epstein-Barr virus infection (TRAF3, PSMD13, SIN3A)." (PMID 36330154, 2022). "Finally, the results of KEGG enrichment analysis showed four significantly enriched pathways (P < 0.05): beta-Alanine metabolism (SMOX, HIBCH), Pathways in cancer (GLI2, AR, TXNRD3, TRAF3, FGF16), Non-homologous end-joining (MRE11), Epstein-Barr virus infection (TRAF3, PSMD13, SIN3A)." (PMID 36330154, 2022).
HCMV infection (1 paper, 2014).
laryngeal carcinoma (1 paper, 2013). Carcinoma that arises from the laryngeal epithelium. "To our knowledge the first prospective investigation of its kind, we have shown that MRE11 and RAD50 genes do not contribute to laryngeal cancer." (PMID 24079363, 2013).
Listeria infection (1 paper, 2017). "Listeria infection was reported to induce DNA damage in HELA cells, with the mechanism involving LLO blocking of the signaling response to DNA breaks through degradation of Mre11 (sensor of DNA damage), which improved replication of the Listeria bacteria." (PMID 28186976, 2017).
metastatic disease (1 paper, 2023). "This may suggest that the effects of elevated MRE11 expression are more pronounced in certain contexts, such as those with advanced metastatic disease." (PMID 37173905, 2023).
metastatic prostate carcinoma (1 paper, 2024). A carcinoma that arises from the prostate gland and has spread to other anatomic sites.
muscular atrophy (1 paper, 2022). The loss of muscle tissue due to inactivity or disease. "Targets of UFMylation include nuclear proteins Histone H4, MRE11, and ACS1 with the latter particularly relevant to the current study given mutations in ACS1 are associated with muscular atrophy." (PMID 36472367, 2022).
neurofibromatosis type 1 (1 paper, 2023). A clinically heterogeneous, neurocutaneous genetic disorder characterized by cafe-au-lait spots, iris Lisch nodules, axillary and inguinal freckling, and multiple neurofibromas. "Interestingly cells from cancer syndromes show either a maximal number of MRE11 foci from 10 min to 1 h after 2 Gy X-rays (e.g., retinoblastoma, tuberous sclerosis complex, and neurofibromatosis type 1) or the MRE11 foci are impaired (e.g., in BRCA1-, BRCA2-, BLM-, FANC-, and ATM-mutated cells)." (PMID 37626928, 2023).
Oculomotor apraxia (1 paper, 2011). Ocular motor apraxia is a deficiency in voluntary, horizontal, lateral, fast eye movements (saccades) with retention of slow pursuit movements. "The previously reported missense mutation W210C in MRE11 gene was identified in two families with autosomal recessive ataxia and oculomotor apraxia." (PMID 21324166, 2011).
renal cell carcinoma (1 paper, 2020). "The NR5A1-derived tumors showed 657 unique proteins that participate in Renal cell carcinoma (CRK, ELOB and PAK3) and Homologous recombination (ATM, BRCC3 and MRE11) among others." (PMID 33261069, 2020).
rhabdomyosarcoma (1 paper, 2022). A rare aggressive malignant mesenchymal neoplasm arising from skeletal muscle. "We examined the accumulation of trapped TOP2 using the ICE bioassay by transiently transfecting RH30 cells, a pediatric rhabdomyosarcoma cell line with siRNA against MRE11 or non-targeting siRNA followed by treatment with etoposide at various concentrations (2, 10, 50 μM) for 2 h." (PMID 36213114, 2022).
serous cystadenocarcinoma (1 paper, 2022). A malignant serous cystic neoplasm usually involving the ovary or the pancreas. "In 199 evaluable tumours, high nuclear Mre11 was associated with serous cystadenocarcinoma (p < 0.001) and high FIGO stage (p = 0.002)." (PMID 35853939, 2022). "High cytoplasmic expression of Mre11 was associated with serous cystadenocarcinoma (p < 0.001) and high grade (p = 0.007) tumours but did not influence survival." (PMID 35853939, 2022). "In the current study, high Mre11 expression was linked with serous cystadenocarcinoma, high-stage, and high-grade disease." (PMID 35853939, 2022). "Furthermore, low Mre11 transcript was associated with pathological response to chemotherapy (p = 0.025) in serous cystadenocarcinomas." (PMID 35853939, 2022).